IL17F (interleukin 17F)
Diseases named in the same sentence as IL17F in open-access papers (continued):
Sharing a sentence is not in itself a finding about the gene and the disease.
asthma (80 papers, 2008 to 2025). "Recent studies have demonstrated that the expression of IL-17F in the airways is positively associated with both the presence of neutrophils and the severity of asthma." (PMID 40564060, 2025). "the IL17F gene encodes the pro-inflammatory cytokine involved inpathophysiological manifestations of asthma." (PMID 37153512, 2023). "Our group has previously demonstrated that single-nucleotide polymorphisms (SNPs) in IL-17A and IL-17F gene regions are potentially associated with the development of AR and comorbid asthma in Chinese subjects." (PMID 33810821, 2021). "Several studies suggest that IL-17A and/or IL-17F are associated with airway inflammatory diseases, such as severe asthma and COPD5,6." (PMID 34075087, 2021). "Intriguingly, a separate study reported that patients homozygous for a SNP that introduces a loss of function mutation in IL-17F protein (H161R) were protected from asthma." (PMID 33424845, 2020). "Th17 cells and their canonical cytokines, IL-17A and IL-17F, are key players in the pathogenesis of asthma and are closely associated with the more severe phenotypes." (PMID 32670268, 2020). "Any epistatic relationship between this IL-17F SNP and the 17q21 asthma-risk SNPs remains to be determined." (PMID 33424845, 2020). "Airway tissues from patients with severe asthma demonstrated increased expression of Th17-associated cytokines, IL-17A, and IL-17F, together with increased expression of IL-8 and excess neutrophilia." (PMID 32670268, 2020). "A previous study on the IL17F His161Arg variant in patients with asthma showed that this polymorphism is protective against asthma and characterised the function of this mutant at the molecular level." (PMID 31831764, 2019). "In studies involving the Th17 pathway, SNVs in the IL17A and the IL17F were associated with allergic rhinitis and asthma." (PMID 31168303, 2019). "Various gene variations associated with the occurrence of asthma and asthma severity, however the genetic role of mRNA IL-17F and IL-17F has not been fully understood." (PMID 28606156, 2017). "A special link between IL-17 and asthma has been concerned, especially IL-17A and IL-17F of the IL-17 family, which were shown to play a pro-inflammatory role in asthma and have the potential association with the disease severity." (PMID 26289446, 2015). "In a case-control study of 867 unrelated Japanese subjects, a His161 to Arg161 (H161R) substitution in the third exon of the IL-17F gene was associated with asthma." (PMID 24829928, 2014). "Increased airway hyperreactivity in response to methacholine in patients with asthma positively correlates with IL-17A levels in the sputum and a polymorphism in IL-17F that results in a loss-of-function mutation is inversely related to asthma risk." (PMID 25177863, 2014). "The associations between SNP rs763780 of IL17F and several diseases, such as asthma, inflammatory bowel disease, and Crohn's disease, have also been investigated." (PMID 23049595, 2012). "IGF1 is produced by human bronchial epithelial cells in response to IL-17F, a cytokine implicated in asthma." (PMID 22235296, 2012). "In the mouse model of asthma, IL-17F is clearly expressed in the lung and is able to cause pulmonary neutrophilia and provides an additive effect on antigen-induced allergic inflammatory responses." (PMID 22013453, 2011). "We have also demonstrated that a coding-region variant (H161R) of the IL-17F gene is inversely associated with asthma and encodes an antagonist for the wild-type IL-17F." (PMID 22013453, 2011). "Several additional studies have shed light on the function of IL17F and further suggested that it is a good candidate asthma susceptibility gene." (PMID 18197984, 2008). "Conversely, IL-17F protein and mRNA seem more closely linked to the severity of asthma than IL-17A." (PMID 37115755, 2023).
asthma (continued). "Current evidence presents that IL-17F rs1889570 could increase risk of asthma by influencing the expression of proinflammatory cytokines, chemokines, and growth factors associated with leukocyte activation and airway remodeling." (PMID 36300118, 2022). "The single nucleotide variation 7488 T/C, located in exon 3 of the IL17F gene, has been studied in relation to susceptibility to various diseases such as ulcerative colitis, asthma, acute myeloid leukemia and various solid tumors, including CRC and gastric cancer." (PMID 36422171, 2022). "High IL‐17 expression, including IL‐17A and IL‐17F, has been implicated in asthma pathogenesis." (PMID 33747463, 2021). "Besides, several reports have shown the association of the IL17F rs763780 SNP with different inflammatory diseases, such as rheumatoid arthritis, inflammatory bowel disease, asthma, Graves' disease, ulcerative colitis, cancer, among others." (PMID 31616423, 2019). "The most studied variants in the IL17F gene (rs763780 and rs2397084) were associated with asthma." (PMID 31168303, 2019). "This suggests that the H161R variant of IL-17f is associated with asthma severity." (PMID 24829928, 2014). "Furthermore, a polymorphism in IL-17F gene that results in a loss of lung function mutation is inversely related to asthma risk." (PMID 22013453, 2011). "In addition, IL17F is located on chromosome 6p, which has been linked to asthma and asthma-related phenotypes in multiple genome scans." (PMID 18197984, 2008). "Following their differentiation, Th17 cells release various cytokines, notably IL-17A, IL-17F, IL-22, and IL-21, with IL-17A being the most extensively studied in the context of asthma pathogenesis." (PMID 40564060, 2025). "IL-17A and IL-17F have the potential to control the influx of neutrophils in conditions such as asthma, lung allograft rejection, and cystic fibrosis." (PMID 38216608, 2024). "It has also been reported that in severe and treatment-resistant asthma, Th17 cell activation leads to the release of inflammatory mediators IL-17A and IL-17F." (PMID 39539452, 2024). "Increased expression of IL-17A and IL-17F mRNA and protein has been observed in individuals with obesity-related asthma, suggesting a unique asthma phenotype." (PMID 39539452, 2024). "IL-17F level is also increased in patients with severe asthma and correlates with airway neutrophilia." (PMID 39194521, 2024). "It has also been found that IL-17A and IL-17F exert different biological effects on the airway inflammation of asthma." (PMID 37377958, 2023). "The proinflammatory cytokine interleukin-17F (IL-17F) expression is also increased in the airways of asthmatics and correlates with asthma severity." (PMID 37686037, 2023). "Noteworthy, although IL-17F belongs to the Th17 lineage, and in sharp contrast with the deleterious asthma outcomes of IL-17A, it has a protective effect on experimental asthma development." (PMID 36233196, 2022). "A previous study demonstrated that mucosa airway biopsies of patients with severe asthma have increased expression of both IL-17A and IL-17F." (PMID 36517803, 2022). "In contrast, other asthma models mimicking more neutrophilic or severe asthma endotypes clearly demonstrated a pathological role for the IL-17A/IL-17F/IL-17RC axis in the modeled diseases." (PMID 35883573, 2022). "IL-17F levels are higher in both mild-to-moderate and severe asthma patients as compared to healthy controls." (PMID 35883573, 2022). "Taken together, these findings indicate that IL-17E acts differently to its relatives IL-17A and IL-17F in asthma pathogenesis." (PMID 35883573, 2022). "In mild-to-moderate asthmatics, the level of IL-17A in the airway submucosal layer was significantly increased, whereas IL-17F was higher in both mild-to-moderate and severe asthma." (PMID 35387016, 2021).
asthma (continued). "Several preclinical and clinical studies reported relatively high level of IL-17, particularly IL-17A and IL-17F, in sputum, nasal and bronchial biopsies, and blood of patients with severe asthma." (PMID 35387016, 2021). "In contrast, Il17f−/− animals exhibit higher Th2 cytokine and eosinophil infiltration in an asthma model, suggesting a suppressive function for IL-17F cytokine." (PMID 35006414, 2021). "We also investigated the effect of VitD supplementation on the expression of proinflammatory cytokines involved in asthma pathogenesis, including Th2 cytokines (IL-4 and IL-5) and Th17 cytokines (IL-17A and IL-17F)." (PMID 34395637, 2021). "Although the role of IL-17F in asthma pathogenesis is well documented, the mechanism regulating its expression is not very well understood." (PMID 34395637, 2021). "This inverse correlation was attributable to the H161R protein functioning as a natural IL-17F antagonist, implying a critical role for IL-17F in asthma pathogenesis." (PMID 33424845, 2020). "Moderate asthma and severe asthma are usually related to the increase of neutrophils and Th17 cytokines such as IL-17A, IL-17F, and IL-22 producing the secretion of epithelial-derived neutrophil chemokines to attract neutrophils in the airways." (PMID 32015750, 2020). "In line with our findings, these data suggest that S. commune can exacerbate asthma by inducing IL-17A– and IL-17F–mediated neutrophilic airway inflammation." (PMID 31852931, 2019). "Another important area of research in which lung organoids are anticipated to be of value is in deciphering IL-17F function in asthma." (PMID 30873173, 2019). "In contrast, il17f−/− animals show a greater infiltration of Th2 cytokines and eosinophils, suggesting a suppressive function of IL17F in asthma." (PMID 31616423, 2019). "IL-17F mediates asthma via IL-17R binding on bronchial epithelial cells, eosinophils, fibroblasts and airway smooth muscle cells." (PMID 30873173, 2019). "In conclusion, we demonstrated that the basidiomycetous fungus S. commune induces neutrophilic airway inflammation in OVA-induced asthma model mice, while IL-17A and IL-17F play central roles in neutrophilic airway inflammation induced by S. commune." (PMID 31852931, 2019). "We demonstrated that S. commune induces neutrophilic airway inflammation in OVA-induced asthma model mice, and IL-17A and IL-17F had central roles in this activity." (PMID 31852931, 2019). "Recent studies illustrated the upregulation of IL-17A and IL-17F in asthma and reported that elevation of IL-17A and IL-17F levels in the lungs is directly correlated with disease severity." (PMID 31852931, 2019). "Intratracheal administration of S. commune to the OVA-induced asthma model mice induced the production of the Th17-related cytokines, IL-17A and IL-17F, as well as Th1-related cytokine INF-γ in the lungs." (PMID 31852931, 2019). "As pro-inflammatory cells, Th17 cells can induce the occurrence of asthma and autoimmune diseases by secreting inflammatory factors such as IL-17A, IL-17F, IL-6 and tumor necrosis factor-α." (PMID 30089474, 2018). "The expression of serum IL-1β, IL-4, and IL-17F were all significantly increased in the asthma model animals when compared with levels in mice from the PBS + PBS group (P < 0.05, P < 0.01, and P < 0.001, respectively)." (PMID 30089474, 2018). "IL‐17F shows several distinctive features of asthma such as airway remodeling, goblet cell hyperplasia, and increasing airway hyperreactivity." (PMID 28474507, 2017). "Collectively, these results provided evidence supporting the potential importance of the Th17‐ASMCs crosstalk via the IL‐17F‐IL‐6 axis in airway inflammation and as a candidate pharmacological target for airway inflammatory diseases such as asthma." (PMID 28474507, 2017). "Animal model studies have also established a causative link between Th17 cells and increased levels of IL-17A and IL-17F with glucocorticoid-insensitive asthma." (PMID 28628664, 2017).
asthma (continued). "Interleukin 17F is a cytokine that plays an important role in the pathophysiology of asthma attacks." (PMID 28606156, 2017). "Interleukin 17F plays role in asthma attacks through various channels, such as affect the levels of respiratory tract neutrophil, stimulates mucus hypersecretion, respiratory hyperreactivity, airway remodeling, and resistance from steroid." (PMID 28606156, 2017). "Accumulating evidence indicates that Th17 cell and Th17 cytokines such as IL-17A, IL-17F and IL-22 contribute to the development of asthma." (PMID 26974537, 2016). "Acupuncture reduced the OVA specific IgE level as well as the Th17 cytokine levels including IL-17A, IL-17F, and IL-22 in the serum of the experimental asthma mice." (PMID 26612993, 2015). "Th17 cytokines which included IL-17A, IL-17F, and IL-22 elevated obviously in asthma group compared to NC group (p < 0.05), and acupuncture exerted inhibitory effect on these cytokine levels (p < 0.05)." (PMID 26612993, 2015). "Immunocytochemistry showed that IL-17F positive cells in the subepithelial component and epithelium are significantly elevated in severe asthma compared with healthy and mild asthmatic subjects." (PMID 24829928, 2014). "In this review, we discuss the finding that IL-17F has a key role in asthma pathology and is a novel drug target for asthma." (PMID 24829928, 2014). "Several studies have demonstrated that IL-17F plays a pivotal role in allergic airway inflammation and induces several asthma-related molecules such as CCL20." (PMID 24829928, 2014). "It is suggested that further investigation of IL-17F is informative in pointing to novel approaches to the diagnosis and treatment of asthma." (PMID 24829928, 2014). "IL-17F is able to induce asthma-related cytokines, chemokines, and adhesion molecules in bronchial epithelial cells." (PMID 24829928, 2014). "Asthma is a common chronic inflammatory disease of the airways and IL-11 and IL17F are considered as critical cytokines in the pathogenesis of airway inflammation." (PMID 24705157, 2013). "Since some phenotypes of asthma cannot be explained using classical Th1/Th2 theory, numerous recent studies have suggested possible roles of IL-17A and IL-17F in asthma." (PMID 24454477, 2013). "Immunocytochemistry showed that IL-17F positive cells in the subepithelial component and epithelium are significantly elevated in severe asthma compared with control and mild asthmatic subjects." (PMID 22013453, 2011). "Th17 cells produce IL-17A, IL-17F, IL-21, IL-22, and TNF-α to perform their functions, and IL-17A and IL-17F are linked to severe asthma with neutrophil inflammation and responsible for corticosteroid resistance in asthma." (PMID 38203353, 2023). "The expression and production of IL-17A and IL-17F is enhanced in patients with asthma." (PMID 35883573, 2022). "The biological activity of IL-17A, IL-17F, and the heterodimer IL-17A/F is increased in asthma." (PMID 36517803, 2022). "Furthermore, in a mouse model of steroid-insensitive toluene diisocyanate-induced asthma, it appears that IL-17F is the driving force behind neutrophil infiltration into the airways and resistance to corticosteroids." (PMID 35883573, 2022). "The neutrophilic inflammation in severe asthma may be orchestrated by Th17 cells and increased expression of IL-17A and IL-17F is described in airways of patients with severe asthma." (PMID 35295917, 2022). "The promotion of inflammation in asthma by IL-17A and IL-17F has been confirmed." (PMID 34180764, 2021). "For example, asthma induced by A. versicolor intratracheally manifested as a strong Th17 cell response along with IL-17A, IL-17F, and IL-22 expression, and co-exposure to the house dust mite and A. versicolor also resulted in a combination of Th2 and Th17 responses." (PMID 33441700, 2021).
asthma (continued). "Previous studies examining the expression of IL-17A and IL-17F in asthmatic patients' airways revealed an increase in IL-17A and IL-17F lung immunoreactivity noted in tissues obtained via bronchoscopy and showed increased IL-17A and IL-17F mRNA expression with increased asthma severity." (PMID 34221020, 2021). "We hypothesized that soluble IL-17RC protein delivered by CS nanoparticles would have the positive effect on asthma, alleviating airway inflammation induced by IL-17 and IL-17F signal pathway." (PMID 34180764, 2021). "For example, patients with asthma have a high level of IL-17F." (PMID 32260590, 2020). "We next hypothesized that IL-17A and IL-17F were involved in neutrophilic airway inflammation induced by S. commune in OVA-induced asthma model mice." (PMID 31852931, 2019). "To demonstrate this hypothesis, we investigated the roles of IL-17A and IL-17F using OVA-induced asthma model mice, generated by knocking out IL-17a and IL-17f (Il-17a−/−Il-17f−/−), and WT mice." (PMID 31852931, 2019). "Similarly to the COPD data, Th17 cells and their corresponding cytokines, IL-17A and IL-17F, appeared to contribute to the pathogenesis of primarily severe and steroid-resistant asthma." (PMID 30380761, 2018). "Interleukin (IL)‐17F plays a critical role in the pathophysiology of asthma." (PMID 28474507, 2017). "Further in vivo study is needed to clarify the importance of the IL‐17F/IL‐6 axis in asthma." (PMID 28474507, 2017). "This implies that IL-17F can be used as a clinical biomarker for asthma diagnosis and management." (PMID 28606156, 2017). "IL‐17F/IL‐6 axis might be involved in the pathophysiology of allergic airway inflammation, and targeting IL‐17F and its signaling pathways could be a novel strategy for asthma." (PMID 28474507, 2017). "In a mouse model of asthma, IL-17F−/− mice exhibited enhanced Th2 response and eosinophil infiltration, while IL-17A−/− mice showed the opposite, suggesting a suppressive role for IL-17F and a promotional role for IL-17A in the induction of asthma through regulating the Th2 response." (PMID 26682905, 2015). "In this regard, a placebo-controlled trial has been recently carried out to evaluate the effects on moderate-to-severe uncontrolled asthma of brodalumab, a human IgG2 anti-IL-17RA monoclonal antibody that blocks the biological activity of both IL-17A and IL-17F." (PMID 25878402, 2015). "IL-17R which responds to IL-17A or IL-17F increased in asthma." (PMID 26612993, 2015). "This implies that IL-17F can be used as a clinical biomarker of asthma diagnosis and management." (PMID 24829928, 2014). "Functional studies have suggested that IL-17F is involved in asthma pathology." (PMID 24829928, 2014). "Recent studies have demonstrated that IL-17F is involved in steroid resistance in asthma." (PMID 24829928, 2014). "However, it remains to be determined which IL-17F-producing cell types contribute to asthma pathogenesis in response to various stimuli in human." (PMID 24829928, 2014). "Hence, increased understanding of the significance of IL-17F would help to uncover the molecular mechanisms of asthma." (PMID 24829928, 2014). "Although both IL-17A and IL-17F have been shown to play a role in asthma, studies of gene knockout mice have suggested that IL-17F may in fact ameliorate the disease process." (PMID 23462708, 2013). "IL-17A and IL-17F, which are proinflammatory cytokines released by Th17 cells and crucially involved in neutrophilic inflammation as well as in airway remodeling, are significantly upregulated in bronchial biopsies obtained from patients with severe asthma." (PMID 23853765, 2013). "Indeed, in lung tissue sections from asthmatic patients there is an overexpression of IL-17A and IL-17F, whose levels correlate with asthma severity, especially in subjects with neutrophilic, steroid-resistant disease." (PMID 23853765, 2013).